CDCA8 (cell division cycle associated 8)
Diseases named in the same sentence as CDCA8 in open-access papers (continued):
Sharing a sentence is not in itself a finding about the gene and the disease.
bladder cancer (continued). "Depending on the median expression of CDCA8 in bladder cancer tissues, the patients were divided into high- and low-expression patients." (PMID 32377458, 2020). "We verified the expression and clinical relevance of CDCA8 in bladder cancer tissues by immunohistochemistry (IHC)." (PMID 32377458, 2020). "Analysis of the relationship between CDCA8 expression and clinical factors in patients with bladder cancer." (PMID 32377458, 2020). "CDCA8 expression in bladder cancer was significantly higher than that in normal tissues (P < 0.001)." (PMID 32377458, 2020). "To further understand the role of CDCA8 in bladder cancer, we studied the functions of CDCA8 in bladder cancer cells in vitro and analysed its possible mechanisms." (PMID 32377458, 2020). "CDCA8 expression in bladder cancer was significantly increased in the GSE13507 dataset (P < 0.001) and in the GSE37815 dataset (P < 0.01)." (PMID 32377458, 2020). "We analysed the correlation between CDCA8 expression and the prognosis of patients with bladder cancer in the GSE13507 dataset." (PMID 32377458, 2020). "CDCA8, functions as a cell cycle regulatory gene, has been reported to participate in the occurrence and development of various cancers such as thyroid and prostate cancer, liver cancer, ovarian cancer and bladder cancer." (PMID 38057871, 2023). "Knocking down CDCA8 inhibits the proliferation of bladder cancer cells and enhances apoptosis." (PMID 35456460, 2022). "Besides, abnormal expression and positive regulatory functions of CDCA8 in clear cell renal cell carcinoma and bladder cancer have also been illuminated." (PMID 33542211, 2021). "In addition, we also used the GSE48075 dataset to analyse the correlation between CDCA8 expression and common mutant genes in bladder cancer." (PMID 32377458, 2020). "Knocking down CDCA8 could inhibit the proliferation, migration and invasion of bladder cancer cells." (PMID 32377458, 2020). "We also verified CDCA8 expression in bladder cancer tissues by immunohistochemistry." (PMID 32377458, 2020). "We divided the samples into two subgroups (high and low CDCA8 expression level subgroups) based on the CDCA8 gene expression values in these 414 bladder cancer samples and used GSEA analysis to predict the pathways that CDCA8 may affect." (PMID 32377458, 2020). "Notably, we also verified the expression of CDCA8 in bladder cancer and its clinical correlation by IHC." (PMID 32377458, 2020). "CDCA8 knockdown can induce the apoptosis of bladder cancer cells." (PMID 32377458, 2020). "We verified CDCA8 expression in seven normal bladder tissues and 35 bladder cancer tissues by IHC." (PMID 32377458, 2020). "CDCA8 was involved in the regulation of the growth cycle of bladder cancer cells." (PMID 32377458, 2020). "The results showed that CDCA8 may have functions of regulating cell DNA binding, DNA repair and cell division in bladder cancer." (PMID 32377458, 2020). "The apoptosis rates of T24 and 5637 cells in si-CDCA8 group were significantly higher than those in si-NC group (P < 0.001), indicating that inhibiting CDCA8 expression could promote the apoptosis of bladder cancer cells." (PMID 32377458, 2020). "Firstly, we studied the mRNA expression of CDCA8 through the Gene Expression Omnibus (GEO) and the Cancer Genome Atlas (TCGA) databases and analysed the correlation between CDCA8 expression and prognosis of patients with bladder cancer." (PMID 32377458, 2020). "However, the specific regulatory mechanisms of CDCA8 in bladder cancer cells require further investigation." (PMID 32377458, 2020). "But the cox multivariable analyses showed that intravesical therapy, N stage, progression were the independent influence factors of overall survival and CDCA8 expression, tumor grade, progression were the independent influence factors of cancer specific survival among bladder cancer patients." (PMID 30142792, 2018).
bladder cancer (continued). "Cox univariable analyses showed intravesical therapy, N stage, tumor grade were the influence factors of overall survival and CDCA8 expression, intravesical therapy, tumor grade, progression were the influence factors of cancer specific survival among bladder cancer patients." (PMID 30142792, 2018). "However, the role of the CDCA8 in bladder cancer is unclear." (PMID 32377458, 2020). "However, the role of CDCA8 in bladder cancer is not fully understood." (PMID 32377458, 2020). "CDCA8 may serve as a potential therapeutic target for patients with bladder cancer." (PMID 32377458, 2020). "However, the correlations of CDCA8 expression with clinicopathological factors and prognosis of bladder cancer (BC) remain unclear." (PMID 30142792, 2018). "To investigate the role of CDCA8 in HCC tissues, we examined CDCA8 mRNA level, which were up-regulated in multiple cancers, including liver cancer, bladder cancer, colorectal cancer, and gastric cancer in the ONCOMINE dataset." (PMID 36639822, 2023). "Hence, CDCA8 may serve as an effective therapeutic target for treatment of bladder cancer." (PMID 32377458, 2020). "Notably, knocking down CDCA8 could induce the apoptosis of bladder cancer cells." (PMID 32377458, 2020). "We found mRNA expression of AURKA, CDCA8, CDC20 were decreased upon knockdown of PUF60 by its specific siRNA, indicating that they are the potential downstream targets of PUF60 in bladder cancer (indicated by the arrows)." (PMID 33117697, 2020). "We also found that CDCA8 expression was higher in advanced bladder cancer than in non-advanced bladder cancer (P < 0.05)." (PMID 32377458, 2020).
liver cancer (15 papers, 2019 to 2025). An epithelial or non-epithelial malignant neoplasm that arises from the liver. "Univariate analysis showed that high CDCA8 expression was associated with poor OS in liver cancer patients, with a hazard ratio (HR) of 1.85 (95% confidence interval [CI]: 1.47–2.32; P = 1.16 × 10–7)." (PMID 33685433, 2021). "Among those signature genes, the CDCA8 is significantly associated with the prognosis and has been verified could be an independent predictor for a poor prognosis in liver cancer." (PMID 40465781, 2025). "However, only a few studies have explored the association between CDCA8 and hepatitis, cirrhosis, and liver cancer." (PMID 33685433, 2021). "In conclusion, we found that the level of CDCA8 expression was increased in liver cancer tissues and associated with a poor prognosis, suggesting that CDCA8 may be a potential prognostic molecular predictor for liver cancer patients." (PMID 33685433, 2021). "Furthermore, CDCA8 deficiency inhibited liver cancer cell proliferation and invasion." (PMID 36855818, 2023). "CCK8 and cloning experiments were then applied to confirm the CDCA8 significance in liver cancer cell proliferation." (PMID 36855818, 2023). "On the other hand, previous literatures revealed that CDCA8 affects liver cancer progression through E2F1 and ATF3." (PMID 36639822, 2023). "Cell functional assays revealed that CDCA8 silencing suppressed liver cancer cell proliferation, invasion, and migration." (PMID 36855818, 2023). "In this study, we sought to use existing data from the TCGA to assess the value of CDCA8 expression in liver cancer prognosis." (PMID 33685433, 2021). "Kaplan–Meier survival analysis indicated that high CDCA8 expression was related to a poor prognosis in liver cancer (P = 2.456 × 10−6)." (PMID 33685433, 2021). "Subsequently, we used the Wilcoxon signed-rank test to determine CDCA8 expression in 57 liver cancer tissues and matched adjacent normal tissues." (PMID 33685433, 2021). "Ultimately, our results showed that increased CDCA8 expression correlated with a poor prognosis in liver cancer." (PMID 33685433, 2021). "Then, GSEA was performed to elucidate the biological pathways regulated by CDCA8 that are involved in the pathogenesis of liver cancer." (PMID 33685433, 2021). "Kaplan–Meier survival analysis was performed to examine the role of CDCA8 expression in predicting the prognosis of liver cancer patients." (PMID 33685433, 2021). "The Wilcoxon rank-sum test was used to compare the difference in CDCA8 expression between liver cancer tissues and matched normal tissues." (PMID 33685433, 2021). "To visualize the expression levels of CDCA8 in normal liver tissues and HCC, we downloaded three typical IHC samples of CDCA8 from normal liver tissues and liver cancer tissues in HPA." (PMID 34741389, 2021). "We aimed to evaluate the potential role of CDCA8 expression in the prognosis of liver cancer by analysing data from The Cancer Genome Atlas (TCGA)." (PMID 33685433, 2021). "Additionally, we analyzed the expression of ADAMTS5, CDCA8, and LDHA, the top three high-risk genes, in a liver cancer tissue array comprising 57 paired liver cancer tissues." (PMID 40647517, 2025). "CDCA8 is a biomarker in many cancers, such as liver cancer, and ovarian cancer, among others." (PMID 38875380, 2024). "CDCA8 could be a promising molecular target in the treatment and prevention of metastasis or recurrence in primary liver cancer." (PMID 35852618, 2023). "Additionally, using logistic regression, we demonstrated that CDCA8 not only exhibited marked differential regulation in liver cancer and adjacent tissues, but also showed differences in various subgroups, such as, T stage, PS, TS, HG, and AFP." (PMID 36855818, 2023). "CDCA8 was reported to be an independent prognostic factor for liver cancer." (PMID 36639822, 2023). "High CDCA8 expression is a potential molecular predictor of a poor prognosis in liver cancer." (PMID 33685433, 2021).
liver cancer (continued). "Our current study focused on the prognostic value of CDCA8 in liver cancer." (PMID 33685433, 2021). "Therefore, CDCA8 overexpression is involved in the pathogenesis of several cancers and has potential value as a prognostic biomarker for liver cancer." (PMID 33685433, 2021). "CDCA8 expression was higher in liver cancer tissues than in matched normal tissues." (PMID 33685433, 2021). "We used the Wilcoxon-rank sum test to analyse the relationship between CDCA8 expression and different tissue characteristics, and the results showed that CDCA8 expression was significantly higher in liver cancer tissues than in normal tissues (P = 1.724 × 10−32)." (PMID 33685433, 2021). "Cox model analysis demonstrated that high CDCA8 expression was an independent prognostic factor in liver cancer, highlighting that CDCA8 may be a potential biomarker for liver cancer prognosis." (PMID 33685433, 2021). "However, the relationship between CDCA8 expression and clinicopathological parameters in liver cancer is unclear." (PMID 33685433, 2021). "Interestingly, we discovered that miR‐191 strongly and positively correlated with several important cell cycle regulators, including CDC25A, CDC7 and CDCA8 in the TCGA liver cancer database." (PMID 31334580, 2019). "Therefore, an increasing expression of CDCA8 lead a higher probability of presenting liver cancer." (PMID 40465781, 2025). "Compared with the adjacent tumor tissue and most liver cancer cells lines, a significant increase expression of G6PD, CDCA8, and CTSC in HCC tissues and liver cancer cells was observed, whereas CXCL9 was significant downregulated." (PMID 38742112, 2024). "In addition, CDCA8 expression status could predict the prognosis of prostate and liver cancers." (PMID 37201027, 2023). "Therefore, we could not assay the expression of CDCA8 with a single cell-based strategy, nor could we clearly assess the direct mechanism by which CDCA8 is involved in the development of liver cancer." (PMID 33685433, 2021).
cutaneous melanoma (14 papers, 2020 to 2024). A primary melanoma arising from atypical melanocytes in the skin. "CDCA8 knockdown is reported to inhibit Rho-associated kinase signaling, inhibiting the proliferation and invasion of cutaneous melanoma cells." (PMID 34082692, 2022). "CDCA8 overexpression has been shown to accelerate the development of cutaneous melanoma and is associated with poor prognosis." (PMID 35354488, 2022). "We also discovered that high CDCA8 expression was related to increased migration, invasion and proliferation of skin melanoma cell lines." (PMID 38961953, 2024). "Of note, CDCA8 silencing inhibits cutaneous melanoma cell line cell proliferation, migration, and invasion." (PMID 36855818, 2023). "We propose that suppressing MYBL2 expression to modulate and reduce CDCA8 levels may be a strategy for cutaneous malignant melanoma treatment." (PMID 38961953, 2024). "We previously reported high CDCA8 mRNA and protein levels in skin melanoma tissues." (PMID 38961953, 2024). "Herein, we hypothesized that MYBL2 may modulate CDCA8 expression and contribute to the development of cutaneous melanoma." (PMID 38961953, 2024). "We proposed that CDCA8 may be transcriptionally controlled by MYBL2 in cutaneous malignant melanoma." (PMID 38961953, 2024). "Additionally, high CDCA8 expression showed a significant correlation with poor survival in patients with cutaneous melanoma." (PMID 33187219, 2020). "CDCA8 promotes the malignant progression of cutaneous melanoma." (PMID 32104702, 2020). "Additionally, our study further elucidates the role of MYBL2 in promoting CDCA8 transcription and the role of MYBL2 as an oncogene in CDCA8-dependent cutaneous malignant melanoma." (PMID 38961953, 2024). "Based on information from ONCOMINE and GEO, the CDCA8 levels are relatively high in cutaneous melanoma versus normal tissues." (PMID 36855818, 2023). "However, whether MYBL2 and CDCA8 play a role in malignant melanoma of the skin has not been clarified." (PMID 38961953, 2024).
hepatocellular carcinoma (13 papers, 2018 to 2026). A malignant tumor that arises from hepatocytes. "In conclusion, our findings suggested that CDCA2, CDCA3, CDCA4, CDCA5, and CDCA8 might have potential diagnostic and prognostic values for hepatocellular carcinoma." (PMID 32913466, 2020). "Big data analysis has revealed the upregulation of cell division cycle associated 8 (CDCA8) in human hepatocellular carcinoma (HCC) and its poorer survival outcome." (PMID 33801424, 2021). "Roessler's 19 two datasets indicated that CDCD3, CDCA4 and CDCA8 were overexpressed in hepatocellular carcinoma." (PMID 32913466, 2020). "In Wurmbach's dataset 20, CDCA2, CDCA3, CDCA4, CDCA5 and CDCA8 were up-regulated in hepatocellular carcinoma (HCC), with fold changes of 1.813, 3.214, 1.832, 2.422 and 1.693, respectively." (PMID 32913466, 2020). "The results showed that PDSS1, SLC7A11 and CDCA8 were significantly upregulated in hepatoma cell lines (P < 0.05)." (PMID 32887635, 2020). "In conclusion, we supposed that CDCA2, CDCA3, CDCA4, CDCA5 and CDCA8 might be oncogenes in hepatocellular carcinoma." (PMID 32913466, 2020). "CDCA8 was reported to stimulate tumor development of hepatocellular carcinoma (HCC) via the potentiation of cell cycle progression factors, such as cyclins, Ki 67, and PCNA." (PMID 39940913, 2025). "Our results indicated that a panel of E2F target gene signature, comprising of HN1, KIF4A, CDCA3, CDCA8 and SSRP1, is a reliable tool for predicting the overall survival of Hepatocellular carcinoma patients, and provided significant reference of clinical risk for Hepatocellular carcinoma patients." (PMID 35591857, 2022). "Although the overexpression of CDCA8 is frequently observed in hepatocellular carcinoma (HCC) tissues, the functions of CDCA8 during HCC development remain to be clarified." (PMID 33801424, 2021). "A previous study discovered that CDCA8 could inhibit the ATF3 tumor suppressor and activate the AKT/β-catenin signalling pathway to promote the development of hepatocellular carcinoma." (PMID 36358852, 2022).
ovarian cancer (13 papers, 2015 to 2024). A primary or metastatic malignant neoplasm involving the ovary. "For example, as an upstream transcription factor of CDCA8, MYBL2 promotes CDCA8 expression and hence improves the sensitivity of ovarian cancer cells to olaparib and DDP." (PMID 37840753, 2023). "Consumption of CDCA8 leads to cell cycle arrest in the G2/M phase, increased DNA damage and apoptosis, and enhanced sensitivity of ovarian cancer cells to cisplatin and olaparib." (PMID 35449575, 2022). "Increased CDCA8 expression in ovarian tissues probably plays a critical role in the development of ovarian cancer through the PLK1 pathway." (PMID 35354488, 2022). "Depletion of CDCA8 leads to cell cycle arrest at the G2/M phase, increases DNA damage and apoptosis, and enhances the sensitivity of ovarian cancer cells to Cisplatin and Olaparib." (PMID 34741389, 2021). "Except for CDCA8, the expression levels of the other genes were statistically significant between ovary cancer tissues and normal ovary tissue from TCGA (The Cancer Genome Atlas) and GTEx (the genotype-tissue expression) data." (PMID 33493131, 2021). "Using quantitative PCR with reverse transcription (RT–qPCR) analysis we quantified expression of HOXD9, CDC42 and CDCA8 in ovarian cancer cell lines (N=14) and ovarian (N=6) and fallopian (N=3) epithelial cells." (PMID 26391404, 2015). "CDCA8 was expressed by all three cell types, and was significantly lower in ovarian epithelial cells compared with ovarian cancer cells (P=5.0 × 10−4) and fallopian epithelial cells (P=2.0 × 10−3)." (PMID 26391404, 2015). "In addition, CDCA8 silencing sensitizes ovarian cancer cells to olaparib and cisplatin via induction of the G2/M phase arrest, acceleration of cell apoptosis, enhancement of DNA damage, and interference with RAD51 accumulation in vitro." (PMID 36855818, 2023). "Moreover, high expression of CDCA8 promoted the proliferation of ovarian cancer cells in vitro and in vivo which increased the tumorigenesis, aggressiveness and chemoresistance of ovarian cancer." (PMID 34116652, 2021). "In ovarian cancer cells, MYBL2 was shown to serve as an upstream transcription factor to CDCA8, directly increasing its expression to alter cell cycle regulation and DNA repair." (PMID 37509213, 2023). "The protein expression levels of CCNA2, CCNB1, CDC20, CDCA8, CDK1, KIF11 and TOP2A were high in ovarian cancer tissues, which was further confirmed via the HPA database." (PMID 34253236, 2021).